ARFGEF3 (ARFGEF family member 3)
Description:
Participates in the regulation of systemic glucose homeostasis, where it negatively regulates insulin granule biogenesis in pancreatic islet beta cells (By similarity). Also regulates glucagon granule production in pancreatic alpha cells (By similarity). Inhibits nuclear translocation of the transcriptional coregulator PHB2 and may enhance estrogen receptor alpha (ESR1) transcriptional activity in breast cancer cells.
Synonyms: BIG3; C6orf92; KIAA1244; dJ171N11.1; PPP1R33; A7322
Tractability: Antibody: UniProt predicts a signal peptide or a membrane-spanning region. PROTAC: its protein half-life has been measured.
Gene: Protein-coding gene on chromosome 6 (138,161,939 to 138,344,663, forward strand). Ensembl gene ENSG00000112379.
Subcellular location: Cytoplasm; Cytoplasmic vesicle, secretory vesicle; Cytoplasmic vesicle, secretory vesicle membrane
Gene Ontology:
Molecular function: guanyl-nucleotide exchange factor activity
Biological process: regulation of ARF protein signal transduction
Cellular component: cytoplasm; transport vesicle; transport vesicle membrane
Genetic constraint (gnomAD): Loss-of-function variants: 93 observed, 188.04 expected, observed/expected ratio (o/e) 0.49, 90% interval 0.42 to 0.59. The upper end of that interval is the gene's LOEUF score, 0.59, which puts it in group 2 of 6, group 1 being the genes least tolerant of losing a copy. Missense variants: 2,263 observed, 2,621 expected, observed/expected ratio (o/e) 0.86, 90% interval 0.83 to 0.89. Synonymous variants: 1,102 observed, 1,068.2 expected, observed/expected ratio (o/e) 1.03, 90% interval 0.98 to 1.08.
Homologues: Orthologues: chimpanzee ARFGEF3 (99% identical), macaque ARFGEF3 (98% identical), pig ARFGEF3 (94% identical), dog ARFGEF3 (94% identical), guinea pig ARFGEF3 (93% identical), mouse Arfgef3 (93% identical), rat Arfgef3 (92% identical), rabbit ARFGEF3 (91% identical), tropical clawed frog arfgef3 (75% identical), zebrafish arfgef3 (73% identical).
Diseases named in the same sentence as ARFGEF3 in open-access papers:
ARFGEF3 is named in the same sentence as 16 diseases in open-access papers, as found by Europe PMC text mining. Sharing a sentence is not in itself a finding about the gene and the disease. The quoted sentences say what the papers report.
Anxiety (1 paper, 2023). Intense feelings of nervousness, tension, or panic often arise in response to interpersonal stresses. "Since GABA receptors have been shown to mediate fast synaptic inhibition in neural circuits implicated in the behavioral responses to stress (Paredes and Ågmo 1992), Arfgef3 upregulation may contribute to the anxiety and stress-related behavior observed in Tph2+/− mice." (PMID 37542675, 2023).
emotional dysregulation (1 paper, 2023). "We identified several molecular markers, including Dgkh, Arfgef3, Kcnh7, Grin2a, Tenm1 and Epha6, implicated in neurodevelopmental deficits and psychiatric conditions featuring impaired cognition and emotional dysregulation." (PMID 37542675, 2023).
lung adenocarcinoma (1 paper, 2024). A carcinoma that arises from the lung and is characterized by the presence of malignant glandular epithelial cells. "The ceRNA mechanism, involving genes like TENM4, XRCC2, HDAC5, CDKN1A, ARFGEF3, SNAP25-AS1, RP11-58O9.2, LINC01164, VLDLR-AS1, and RP11-14I17.2, may play a role in lung adenocarcinoma (LUAD) development linked to tumor hypoxia." (PMID 39236027, 2024).
ARFGEF3 also shares sentences with these, for which no sentence is quoted: gastric cancer (9 papers); tumor (6); cancer (4); breast cancer (3); hepatocellular carcinoma (2); lymph node metastasis (2); brain cancer (1); chronic lymphocytic leukemia (1); colon cancer (1); non‐small cell lung cancer (1); ovarian carcinoma (1); pancreatic adenocarcinoma (1); prostate carcinoma (1).